FKBP10 (FKBP prolyl isomerase 10)
Diseases named in the same sentence as FKBP10 in open-access papers (continued):
Sharing a sentence is not in itself a finding about the gene and the disease.
tumor (27 papers, 2016 to 2026). "S5, O and P), suggesting that NACC1 or FKBP10 loss suppresses tumor growth by augmenting antitumor immunity." (PMID 37406115, 2023). "One possible cause of the immunosuppression caused by FKBP10 is that collagen can act as a regulator for tumor associated immune infiltration." (PMID 35096583, 2021). "Among them, FKBP10 was the top protein associated with tumor progression." (PMID 39781460, 2025). "The results showed that the mRNA and protein levels of FKBP10 were significantly increased in tumor tissues compared to benign tissues." (PMID 38233415, 2024). "Comparisons of in vivo imaging and tumor weights confirmed that renal orthotopic tumors after knocking down FKBP10 were significantly inhibited compared with the control group, and no metastases were detected at other sites." (PMID 38233415, 2024). "Multiple studies have suggested that FKBP10 is highly expressed in tumor tissues and is considered as a therapeutic target for ccRCC through experimental and bioinformatics approaches, but there is a lack of further in-depth studies." (PMID 38233415, 2024). "The results showed that FKBP10 protein expression in tumor tissues was significantly higher than that in adjacent benign tissues." (PMID 38233415, 2024). "Inhibition of NACC1 and FKBP10 in tumor cells enhances CD8+ T cell recruitment to limit tumor growth by a number of possibilities." (PMID 37406115, 2023). "In immune-competent mice, NACC1 or FKBP10 depletion attenuated tumor growth, 26.7% (sh336) to 37.6% (sh334) and 42.9% (sh876) to 46.8% (sh486), respectively." (PMID 37406115, 2023). "The expressions of NOX4 and FKBP10 were significantly higher in STAD tumor tissues than those in the paired adjacent normal tissues, respectively (all P < 0.05)." (PMID 36915111, 2023). "Overexpression of FKBP10 is find to boost cancer progression by restrict antitumor immunity or activate tumor-related signaling pathways." (PMID 36709279, 2023). "In this study, we analyzed the expression of FKBP10 in tumor tissues using online databases (TCGA) as well as our CRC cohort, and investigated the relationship between its subcellular expression pattern and patient outcomes." (PMID 37511172, 2023). "In mechanism, circREEP3 recruits the chromatin remodeler CHD7 to initiate FKBP10 transcription in the nucleus and inhibits anti‐tumor immunity by enhancing RNF125‐dependent degradation of RIG‐1 in the cytoplasm." (PMID 35233964, 2022). "We found that FKBP10 was highly expressed in cancerous tissues, positively related to tumor grade and poor prognosis of patients." (PMID 33557829, 2021). "Furthermore, targeting FKBP10 synergized with anti-PD-1 therapy in suppressing tumor growth in vivo." (PMID 41694575, 2026). "The function of FKBP10 in tumor progression varies by cancer type." (PMID 39781460, 2025). "To further explore the tumorigenic capacity of FKBP10 in ccRCC, we used cell lines derived xenograft (CDX) model subcutaneously injected with RENCA cells, which showed that FKBP10 knockdown or overexpressed could inhibit or promote tumor growth in vivo." (PMID 38233415, 2024). "Particularly, ek2 is distinguished in transcription regulation and biological function, because it enriched FKBP10, a promoter for tumor proliferation and invasion through the crosstalk to PIK3 pathway, BCL11A and MSC, the tumor stemness-related transcription factors." (PMID 38331768, 2024). "Of nine genes down-regulated by NR2F6 loss, NACC1 and FKBP10 were negatively correlated with the IFN-γ signature, while high NACC1 and FKBP10 expression was associated with poor overall survival, patterns seen upon tumor-intrinsic NR2F6 inactivation." (PMID 37406115, 2023). "To determine whether candidate NR2F6 effectors exhibit antitumor activity, we asked whether NACC1 and/or FKBP10 loss would phenocopy NR2F6 loss and attenuate tumor growth." (PMID 37406115, 2023).
tumor (continued). "In addition, the tumor sphere formation assay indicated that the ability to inhibit the tumor sphere formation in 786-O cells with the knockdown of FKBP10 after stable VSX1 overexpression was stronger than that in the shNC group." (PMID 36463181, 2022). "In tumor tissues, FKBP10 protein was located in the cytoplasm of cancerous cells." (PMID 33557829, 2021). "Notably, the combined loss of NACC1 and FKBP10 further decreased tumor growth (by 52.8%) in immune-competent but not immune-compromised mice, again without altering cell growth in vitro." (PMID 37406115, 2023). "Thus, FKBP10 may act as tumor promoter or suppressor in the process of tumor genesis and development depending on the cancer type." (PMID 33557829, 2021). "Mechanistically, we demonstrated that FKBP10 not only promoted EMT but also activated the MEK/ERK/ELF3 signaling axis, leading to an increased secretion of CXCL8 by tumor cells." (PMID 41694575, 2026). "The higher the mRNA or protein expression of FKBP10 in tumor tissues, the higher the pathological grade or TNM stage of the tumor." (PMID 38233415, 2024). "Higher expressions of NOX4 and FKBP10, and lower expressions of ALDH3A2 and MAOA were observed in tumor samples compared with the normal tissues, respectively." (PMID 36915111, 2023). "Our findings establish a tumor-intrinsic function for NR2F6 and identify NACC1 and FKBP10 as their downstream effectors in inhibiting antitumor immunity." (PMID 37406115, 2023). "Successively, we investigated the prognostic value of FKBP10 expression patterns in relation to different TNM stages, tumor location and the adoption of chemotherapy." (PMID 37511172, 2023). "Three of the identified key genes (FKBP10, KRT19, and SPANXB1) negatively correlated with the infiltration of CD8+ T cells, which is the lymphocytes primarily responsible for immune-mediated tumor cell death." (PMID 35096583, 2021). "Patients overexpressing ANXA5, FKBP10, MSN, and PYGL in the tumor tissues had significantly shorter OS compared to the low expressed group in IS1–IS3 subtypes." (PMID 34512630, 2021). "This asRNA is located in the locus containing genes JUP, FKBP10, HAP1, LEPREL4 and EIF1 upregulated in HPV16+ tumours." (PMID 29263803, 2016). "In the present study, based on immunohistochemical experiments, we verified the differences in the expression levels of FKBP10 and S1PR4 in different differentiation states and different tumor stages, further demonstrating the plausibility of the results of this study." (PMID 36341424, 2022). "The results of our experiments suggested that FKBP10 and FKBP11 might play important roles in the maintenance of the tumor characteristics of ccRCC." (PMID 34476212, 2021). "qRT-PCR results showed that the expression of FKBP10 and FKBP11 was increased in tumor tissue." (PMID 34476212, 2021). "The results showed that FKBP10 and FKBP11 have a low degree of methylation in tumor tissues." (PMID 34476212, 2021). "FKBP10 promotes tumor cell invasion, migration, and metastasis, but not proliferation." (PMID 39781460, 2025). "No FKBP10-positive cells were found in the non-tumor brain tissue." (PMID 37201304, 2023). "Thus, ANXA5, FKBP10, MSN, and PYGL might be presented by APCs to the T cells and recognized by the B cells to induce a tumor response." (PMID 34512630, 2021). "More accurately, tumor stroma might play an important role in negative immunoregulation since the hub genes (i.e., CTHRC1, COL1A1, LOXL2, P4HA3, and FKBP10) related to immunosuppressive GO terms usually participate in collagen formation." (PMID 33791227, 2021).
cancer (18 papers, 2017 to 2026). A tumor composed of atypical neoplastic, often pleomorphic cells that invade other tissues. "Single-cell profiling revealed that FKBP10 was predominantly expressed in cancer-associated fibroblasts (CAFs, 51.5% of stromal cells), implicating CAF-mediated stromal remodeling in resistance." (PMID 41969611, 2026). "FKBP10 has also been reported to be associated with cancer development, especially in gastrointestinal cancers." (PMID 37511172, 2023). "Intriguingly, cancer cells displayed the elevated FKBP10 expression when invading into the muscle layer of the bladder." (PMID 39781460, 2025). "HE staining revealed that in the control group, cancer cells extensively invaded into muscle layer, whereas FKBP10-knockdown cells retained in the mucosal or submucosal layer." (PMID 39781460, 2025). "FKBP10 is a member of the FK506-binding protein (FKBP) family and has been implicated in cancer development." (PMID 39684755, 2024). "Studies have found that FKBP10 is involved in the progression of idiopathic pulmonary fibrosis, osteogenesis imperfecta and cancers including lung cancer, ovarian cancer, prostate cancer and leukemia." (PMID 38233415, 2024). "Meanwhile, FKBP10 negatively regulated by HIF2α is identified as a novel target of ccRCC with a cancer-promoting role, which seems a rather paradoxical finding." (PMID 38233415, 2024). "It has been reported that a cancer-specific molecular mechanism for NSCLC was related with FKBP10-dependent protein translation." (PMID 36915111, 2023). "As an ER resident protein, the distribution of FKBP10 in cancer tissues was consistent with its role." (PMID 37511172, 2023). "FKBP10, a member of the FK506-binding protein (FKBP) family, has been implicated in cancer development, although its prognostic function remains controversial." (PMID 37511172, 2023). "Most cancers just mentioned presented an FKBP10 positively correlated behavior, i.e., high expression level of FKBP10 promotes cancer and predicts poor prognosis." (PMID 34388114, 2021). "FKBP10 can promote cancer cell proliferation, migration, invasion and metastasis 19-22." (PMID 39781460, 2025). "Extensive research on the wider consequences of FKBP10 interactions in renal and maybe other malignancies may shed light on both generic and targeted anti-cancer treatments." (PMID 39968078, 2025). "However, a dispersive expression of FKBP10 (FKBP10-D) was observed in 44% of cancer tissues, indicating a change in function and potential impact on the development of CRC." (PMID 37511172, 2023). "Most of members were downregulated in different cancer types except FKBP10." (PMID 34476212, 2021). "ER stress emerges as a novel cancer treatment mechanism in the recent decade based on the theory that cells tend to undergo apoptosis when ER proteins, including FKBP10, fail to correctly fold protein precursors to be synthesized afterwards such as pro-collagen." (PMID 34388114, 2021). "Recent studies revealed that FKBP10 was actively involved in cancers." (PMID 34388114, 2021). "KRT19 (AUC = 0.855, CI = 0.825 - 0.885) and FKBP10 (AUC = 0.836, CI = 0.808 - 0.864) had a certain accuracy in predicting cancer and normal, and the predictive abilities of GSK3B (AUC = 0.654, CI = 0.613 - 0.696) and SPANXB1 (AUC = 0.682, CI = 0.650 - 0.714) were less accurate." (PMID 35096583, 2021). "In cancer, aberrant epigenetic regulation of FKBP10 predicts poor clinical prognosis." (PMID 32117864, 2020). "FKBP10‐high tumors showed enhanced ECM remodeling, metabolic reprogramming, and apoptosis resistance, accompanied by an immunosuppressive microenvironment with reduced cytotoxic T cells and enrichment of myeloid‐derived suppressor cells and cancer‐associated fibroblasts." (PMID 41934915, 2026). "Thus, FKBP10 plays an important role in cancer development and may serve as a potential target for therapeutic drugs." (PMID 37201304, 2023). "Therefore, more research is required to determine the significance of FKBP10 in cancer." (PMID 37511172, 2023).
cancer (continued). "However, the function of FKBP10 in cancer is still under debate." (PMID 37511172, 2023). "Furthermore, FKBP10 may be a candidate therapeutic target for ccRCC patients or other cancer types with high FKBP10 level." (PMID 34388114, 2021). "However, the exact mechanism of FKBP10 in ccRCC remains unclear, its role in collagen synthesis and cancer cell proliferation needs to be elucidated." (PMID 34388114, 2021). "KRT19, FKBP10, GSK3B, and SPANXB1 have been investigated at the single-cell level in 9, 10, 16 and 3 types of cancer, respectively." (PMID 35096583, 2021). "FKBP10 was reported to be overexpressed in many cancers and not found in normal tissues around malignant tumors." (PMID 37201304, 2023). "The genes—including BEST4, LMO1, ARID3C, TMEM44, FKBP10, and TRIB3—were correlated with VSX1 and might play a primary role in the transcriptional misregulation of cancer from the TCGA database." (PMID 36463181, 2022). "We compared transcriptional levels of FKBP10, PLOD2 and pro-collagen I chains in cancer tissues with normal samples by inquiring ONCOMINE database." (PMID 34388114, 2021).
FKBP10 also shares sentences with these, for which no sentence is quoted: Bruck syndrome 1 (3 papers); arthrogryposis (2); infection (2); osteogenesis imperfecta type 3 (2); pancreatic carcinoma (2); prostate carcinoma (2); adenocarcinoma (1); connective tissue disease (1); COVID-19 (1); craniosynostosis (1); exophthalmos (1); hepatoblastoma (1); Hydrocephalus (1); hyperplastic polyp (1); odontochondrodysplasia (1); Osteogenesis Imperfecta type (1); osteosarcoma (1); ovarian carcinoma (1); papillary thyroid cancer (1); pterygium (1); rectum adenocarcinoma (1); rheumatoid arthritis (1); skeletal system disease (1); small cell lung carcinoma (1); stomach cancers (1); synovial sarcoma (1); triple-negative breast carcinoma (1); villous adenoma (1).